SREBF2 (sterol regulatory element binding transcription factor 2)
Description:
[Sterol regulatory element-binding protein 2]: Precursor of the transcription factor form (Processed sterol regulatory element-binding protein 2), which is embedded in the endoplasmic reticulum membrane. Low sterol concentrations promote processing of this form, releasing the transcription factor form that translocates into the nucleus and activates transcription of genes involved in cholesterol biosynthesis. [Processed sterol regulatory element-binding protein 2]: Key transcription factor that regulates expression of genes involved in cholesterol biosynthesis. Binds to the sterol regulatory element 1 (SRE-1) (5'-ATCACCCCAC-3'). Has dual sequence specificity binding to both an E-box motif (5'-ATCACGTGA-3') and to SRE-1 (5'-ATCACCCCAC-3'). Regulates transcription of genes related to cholesterol synthesis pathway.
Synonyms: SREBP-2; bHLHd2; SREBP2
Tractability: Small molecule: it belongs to a druggable protein family. Antibody: UniProt predicts a signal peptide or a membrane-spanning region. PROTAC: UniProt records ubiquitination sites on it; ubiquitination databases record sites on it; a small molecule that binds it is known.
Target class: Transcription factor
Gene: Protein-coding gene on chromosome 22 (41,833,099 to 41,907,308, forward strand). Ensembl gene ENSG00000198911.
Subcellular location: Endoplasmic reticulum membrane (Sterol regulatory element-binding protein 2); Golgi apparatus membrane; Cytoplasmic vesicle, COPII-coated vesicle membrane; Nucleus (Processed sterol regulatory element-binding protein 2)
Subcellular location (Human Protein Atlas): Nucleoplasm; Vesicles; Endoplasmic reticulum
Pathways (Reactome):
Metabolism: Activation of gene expression by SREBF (SREBP); PPARA activates gene expression; Regulation of cholesterol biosynthesis by SREBP (SREBF); Zymostenol biosynthesis via lathosterol (Kandutsch-Russell pathway)
Developmental Biology: EGR2 and SOX10-mediated initiation of Schwann cell myelination; Transcriptional regulation of white adipocyte differentiation
Gene Ontology:
Molecular function: C-8 sterol isomerase activity; DNA-binding transcription factor activity, RNA polymerase II-specific; DNA-binding transcription repressor activity, RNA polymerase II-specific; E-box binding; protein binding; RNA polymerase II cis-regulatory region sequence-specific DNA binding; sequence-specific double-stranded DNA binding; DNA binding; DNA-binding transcription activator activity, RNA polymerase II-specific; DNA-binding transcription factor activity; protein dimerization activity; transcription cis-regulatory region binding
Biological process: cellular response to low-density lipoprotein particle stimulus; cellular response to starvation; negative regulation of amyloid-beta clearance; negative regulation of cholesterol efflux; negative regulation of transcription by RNA polymerase II; positive regulation of cholesterol biosynthetic process; positive regulation of cholesterol storage; positive regulation of establishment of protein localization to mitochondrion; positive regulation of transcription by RNA polymerase II; regulation of mitophagy; SREBP signaling pathway; cellular response to laminar fluid shear stress; cholesterol metabolic process; lipid metabolic process; regulation of Notch signaling pathway; regulation of transcription by RNA polymerase II; positive regulation of miRNA transcription
Cellular component: cytoplasm; endoplasmic reticulum; Golgi membrane; nucleoplasm; nucleus; SREBP-SCAP complex; SREBP-SCAP-Insig complex; chromatin; cytosol; endoplasmic reticulum membrane; Golgi apparatus; ER to Golgi transport vesicle membrane; membrane
Genetic constraint (gnomAD): Loss-of-function variants: 51 observed, 108.57 expected, observed/expected ratio (o/e) 0.47, 90% interval 0.37 to 0.59. The upper end of that interval is the gene's LOEUF score, 0.59, which puts it in group 2 of 6, group 1 being the genes least tolerant of losing a copy. Missense variants: 1,343 observed, 1,493.6 expected, observed/expected ratio (o/e) 0.9, 90% interval 0.86 to 0.94. Synonymous variants: 589 observed, 602.33 expected, observed/expected ratio (o/e) 0.98, 90% interval 0.91 to 1.05.
Homologues: Orthologues: chimpanzee SREBF2 (99% identical), macaque SREBF2 (95% identical), guinea pig SREBF2 (94% identical), pig SREBF2 (94% identical), rat Srebf2 (92% identical), rabbit SREBF2 (92% identical), mouse Srebf2 (92% identical), dog SREBF2 (91% identical), tropical clawed frog srebf2 (68% identical), zebrafish srebf2 (50% identical). Paralogues in human: SREBF1 (44% identical), USF2 (9% identical), USF1 (8% identical).
Diseases named in the same sentence as SREBF2 in open-access papers:
SREBF2 is named in the same sentence as 203 diseases in open-access papers, as found by Europe PMC text mining. Sharing a sentence is not in itself a finding about the gene and the disease. The quoted sentences say what the papers report.
Hepatic steatosis (46 papers, 2011 to 2026). Steatosis is a term used to denote lipid accumulation within hepatocytes. "In humans, some studies associate SREBF2 variants with hypercholesterolemia, insulin resistance, DM and liver steatosis." (PMID 33066385, 2020). "Administration of AT extract ameliorated HFD-induced hepatic steatosis induced with decreased expression of lipogenesis-related genes, including Srebf2 and Mlxipl in the liver." (PMID 38612554, 2024). "The phenotypic similarities between hepatocyte-Srebf-2-/- and hepatocyte-Scap-/- mice also suggest that blocking SREBP-2 action would be effective in preventing the development of hepatic steatosis in mice with insulin resistance and/or diabetes." (PMID 28244871, 2017). "However, SR treatment attenuated HFD-induced hepatic steatosis by suppressing TG contents and the expression of fatty acid transport- and lipogenesis-related genes including Fabp1, Fabp4, Slc27a5, Pparg, Mlxipl, Srebf1, Srebf2, Fas, Dgat1, and Dgat2." (PMID 35454963, 2022). "Irisin, a myokine that promotes energy expenditure, has also been shown to improve hepatic steatosis by activating AMP-activated protein kinase and by inhibiting transcription of sterol regulatory element-binding transcription factor 2 in hepatocytes." (PMID 33562473, 2021). "An upstream regulator analysis indicated that PPARα and XBP1 were the top 2 predicted transcription activators involved in the process of hepatic steatosis induced by OSI-906, whereas pathways related to SREBF2 and lysophosphatidylcholine were identified in the linagliptin-treated group." (PMID 33105604, 2020). "Thus, FGF19 and NGM282 appear to selectively modulate LXR signaling, upregulating canonical LXR target genes (Abcg5, Abcg8, Scarb1, Srebf1, Fasn, Scd1, Srebf2, and Scap) without inducing hepatic steatosis." (PMID 30679232, 2019).
hepatocellular carcinoma (44 papers, 2008 to 2026). A malignant tumor that arises from hepatocytes. "The Idh1 promoter is activated by Srebf1a and Srebf2 in human hepatoma cells." (PMID 18959802, 2008). "Additionally, SREBF2 facilitated the upregulation of STARD4 by directly binding to its promoter region, thereby inducing elevated levels of mitochondrial cholesterol, and contributing to the resistance of hepatocellular carcinoma against sorafenib." (PMID 38840241, 2024).
atherosclerosis (43 papers, 2008 to 2025). A disease characterized by the build-up of fatty material and calcium deposition in the arterial wall resulting in partial or complete occlusion of the arterial lumen. "Diseases associated with SREBF2 include atherosclerosis and adrenoleukodystrophy." (PMID 38840241, 2024). "The role of SREBF2 in lipid metabolism makes this gene a candidate responsible for ADH, a group of very frequent diseases that predispose one to atherosclerosis." (PMID 35625914, 2022). "Otherwise SREBF2 transcript was found to be progressively up-regulated in fatty streaks and fibrous lipid plaques, supporting an active role of this biomolecule during the atherosclerosis progression." (PMID 30673762, 2019). "We conclude that SREBF-2 and SCAP may be implicated in the progression of atherosclerosis and the risk of developing SCD." (PMID 19116028, 2008). "Collectively, these genes link SREBF2 to NOX2-based excessive production of reactive oxygen species (ROS), which oxidize HDL and convert it into a pro-inflammatory form (oxHDL) that contributes to atherosclerosis." (PMID 41278993, 2025). "As regulators of this cholesterol metabolism, SREBF-2 and SCAP might play a role in the progression of atherosclerosis." (PMID 19116028, 2008). "Given the central role of the SREBF-SCAP pathway in the regulation of cholesterol, the variation in the SREBF-2 and SCAP locus might affect the progression of atherosclerosis." (PMID 19116028, 2008).
Hypercholesterolemia (35 papers, 2008 to 2026). An increased concentration of cholesterol in the blood. "SREBF2 has also been shown to modulate cholesterol levels: the p.A595G polymorphism diminishes SREBF2 cleavage in vitro and is associated with higher cholesterol levels in patients with polygenic hypercholesterolemia." (PMID 35625914, 2022). "Previous findings have suggested the possibility that SREBF2 mutations are a cause of hypercholesterolemia." (PMID 35625914, 2022). "We found a novel mutation in the SREBF2 gene that increases transcription levels and cosegregates with hypercholesterolemia, and we found increased glucose levels in one family." (PMID 35625914, 2022). "The found mutation may involve the SREBF2 gene in hypercholesterolemia combined with hyperglycemia." (PMID 35625914, 2022). "Our gene expression results with human tissues are in agreement with in vivo findings indicating that SREBF-2 is down-regulated by hypercholesterolemia in porcine aortas." (PMID 19116028, 2008). "Moreover, we explored a possible link between liver Pcsk9, Srebf-2 (SREBP-2 as a positive regulator of Pcsk9 gene expression) genes expression and hypercholesterolemia observed in rats with CRF." (PMID 26481479, 2016). "Coordinated up-regulation of Srebf-2 and Pcsk9 genes expression suggests that SREBP-2 may play a crucial role in regulation of Pcsk9 gene expression and consequently contribute to hypercholesterolemia observed in subjects with CKD." (PMID 26481479, 2016). "The coordinated up-regulation of Pcsk9 and Srebf-2 genes expression suggests that SREBF-2 may play a key role in regulation of Pcsk9 gene expression, circulating PCSK9 level, and hypercholesterolemia in experimental CRF." (PMID 26481479, 2016).
breast cancer (34 papers, 2009 to 2025). A primary or metastatic malignant neoplasm involving the breast. "Recently, CTBP2 has been linked to the inhibition of cholesterol synthesis in breast cancer cells through direct repression of SREBF2 expression." (PMID 36414381, 2023). "We confirmed the relationship between miR-874 and PMVK expression and between miR-874 and SREBF2 expression in clinical specimens by analysing the TCGA breast cancer dataset." (PMID 36323841, 2022). "SREBF2 gene is a lipogenesis transcription factor which has been shown to be up-regulated in a breast cancer cell line (HCC1143) compared to normal mammary epithelial cells (MCF10A)." (PMID 26317411, 2015). "To validate the RNA-seq results, we assessed whether miR-874 affects endogenous PMVK and SREBF2 expression in breast cancer cell lines." (PMID 36323841, 2022).
Obesity (30 papers, 2012 to 2025). Accumulation of substantial excess body fat. "In this study, we investigated the association of the SREBF2 gene (rs1052717, rs2267439, and rs2267443) polymorphisms with obesity and dyslipidemia; a relationship between dyslipidemia and the SREBF2 gene rs2267443 (G/A) polymorphism was found." (PMID 34683084, 2021). "In this study, we investigated the association of SREBF2 gene polymorphisms with obesity and dyslipidemia in psychotic disorder patients treated with risperidone." (PMID 34683084, 2021). "In conclusion, this is the first study of the relationship between the SREBF2 gene and INSIG2 polymorphisms and obesity and dyslipidemia in Thai psychotic disorder patients treated with risperidone." (PMID 34683084, 2021). "This is the first study of the association between the SREBF2 gene and INSIG2 polymorphisms and obesity and dyslipidemia in Thai psychotic disorder patients treated with risperidone." (PMID 34683084, 2021). "Considering the prominent role of these genes in metabolic adverse effects, we hypothesized that the genetic SREBF2 gene and INSIG2 polymorphisms might be involved in the increased risk of obesity and dyslipidemia in Thai patients treated with risperidone." (PMID 34683084, 2021). "The objective of this study was to examine the association of the SREBF2 gene (rs1052717, rs2267439, and rs2267443) and INSIG2 (rs7566605, rs11123469, and rs17587100) polymorphisms on the presence of obesity and dyslipidemia in Thai psychotic disorder patients treated with risperidone." (PMID 34683084, 2021). "The results showed that none of the SREBF2 gene (rs1052717, rs2267439, and rs2267443) polymorphisms were related to the obesity in Thai psychotic disorder patients receiving risperidone." (PMID 34683084, 2021). "Sterol Regulatory Element Binding Transcription Factor 2 (Srebf2), the master regulator of cholesterol biosynthesis, was decreased in ABA and increased during obesity." (PMID 37582711, 2023). "Further studies are needed to assess the role of the SREBF2 gene and INSIG2 in obesity and dyslipidemia." (PMID 34683084, 2021). "The SREBF2 gene and INSIG2 may be candidate genes for risperidone-induced dyslipidemia, obesity, and cardiovascular diseases in psychotic disorder patients." (PMID 34683084, 2021). "Further studies are required to determine the impact of the SREBF2 and INSIG2 allelic forms on the response of obesity and dyslipidemia in the cells of rats exposed to risperidone for the elucidation of the functional consequence of the SREBF2 gene and INSIG2 polymorphisms." (PMID 34683084, 2021). "Our findings indicate that the let-7a-5p/Srebf2 and let-7a-5p/Thbs1/PI3K-AKT-mTOR axes may be crucial in regulating animal lipid accumulation and may contribute to the development of new therapies for obesity." (PMID 38255968, 2024). "In conclusion, our findings suggest that the let-7a-5p/Srebf2 and let-7a-5p/Thbs1/PI3K-AKT-mTOR axes are crucial for lipid accumulation and that they may represent a potential mechanism for controlling lipid accumulation in obesity." (PMID 38255968, 2024). "In conclusion, our study highlights the physiological significance of let-7a-5p in lipid accumulation and suggests that the let-7a-5p/Srebf2 and let-7a-5p/Thbs1/PI3K-AKT-mTOR axes may represent potential mechanisms for controlling lipid accumulation in obesity." (PMID 38255968, 2024).
prostate carcinoma (24 papers, 2009 to 2025). A carcinoma that arises from epithelial cells of the prostate gland. "SREBP2, encoded by the SREBF2 gene, has been demonstrated to support cell survival in prostate cancer through accumulation of cholesterol, and its inhibition is suggested as a potential cancer therapy." (PMID 32028644, 2020). "Exogenous introduction of this microRNA into cells decreases SREBF2 expression at both the mRNA and protein levels, demonstrating a tumor-suppressive role for miR-28-5p in prostate cancer." (PMID 40563399, 2025). "The transcription factor SREBF2 is an oncogenic protein that, in prostate cancer, regulates proliferation, cell survival, and the ability of cancer cells to migrate and invade." (PMID 40563399, 2025). "It was found that SREBF2 is one of the mediators of the tumor suppressor activity of miR-28-5p in prostatic carcinoma cells, and the inhibition of SREBF2 expression can significantly affect the progression of prostate tumors." (PMID 34823420, 2021). "To verify the role of SREBF2 in prostate cancer cells, we silenced SREBF2 in DU-145 cells and 48 h later we evaluated several cellular readouts." (PMID 32028704, 2020). "We focused on the transcription factor SREBF2 as it is a potential oncogenic transcription factor in prostate cancer." (PMID 32028704, 2020). "Paradoxically, SREBF2 has been reported to be increased in prostate cancer, which would be predicted to increase miR-33a levels potentially leading to tumor suppression." (PMID 28947967, 2017). "miR-33a is an intronic miRNA embedded within SREBF2 that has been reported to have tumor suppressive properties in some cancers but has not been examined in prostate cancer." (PMID 28947967, 2017). "Levels of miR-33a are not correlated with SREBF2 levels, implying posttranscriptional regulation of its expression in prostate cancer." (PMID 28947967, 2017).
dyslipidemia (23 papers, 2015 to 2026). "Metabolic syndrome as a whole was also linked to the presence of the Sterol Regulatory Element Binding Transcription Factor 2 (SREBF2) A allele in patients." (PMID 36980961, 2023). "Further corroborations were reported in a Chinese cohort treated with clozapine; with two SREBF2 SNPs being associated with increased risk for the drug-induced metabolic syndrome." (PMID 34575210, 2021). "This study provided evidence of an association between the genetic polymorphisms of SREBF2 (rs2267443) and INSIG2 (rs11123469) with dyslipidemia in Thai psychotic disorder patients receiving risperidone treatment." (PMID 34683084, 2021). "In the future, longitudinal follow-up studies with larger sample sizes are needed to confirm the roles of the SREBF2 gene and INSIG polymorphisms in dyslipidemia in patients treated with risperidone." (PMID 34683084, 2021). "SREBF2 and INSIG2 might be candidate genes for dyslipidemia in people with autism spectrum disorder treated with risperidone." (PMID 38375208, 2023).
COVID-19 (22 papers, 2020 to 2025). A disease caused by infection with severe acute respiratory syndrome coronavirus 2. "Moreover, SREBF2 mRNA, sestrin 1 (SESN1), and proprotein convertase subtilisin/kexin type 9 (PCSK9) RNA levels were increased in PBMCs in COVID-19 patients in a severity-dependent manner." (PMID 34944005, 2021).